ZNF681 (zinc finger protein 681)
Description:
May be involved in transcriptional regulation.
Synonyms: FLJ31526
Tractability: PROTAC: ubiquitination databases record sites on it.
Gene: Protein-coding gene on chromosome 19 (23,739,195 to 23,758,891, reverse strand). Ensembl gene ENSG00000196172.
Subcellular location: Nucleus
Pathways (Reactome):
Gene expression (Transcription): Generic Transcription Pathway
Gene Ontology:
Molecular function: DNA-binding transcription factor activity, RNA polymerase II-specific; RNA polymerase II cis-regulatory region sequence-specific DNA binding
Biological process: regulation of transcription by RNA polymerase II; regulation of DNA-templated transcription
Cellular component: nucleus
Genetic constraint (gnomAD): Loss-of-function variants: 35 observed, 53.37 expected, observed/expected ratio (o/e) 0.66, 90% interval 0.5 to 0.87. The upper end of that interval is the gene's LOEUF score, 0.87, which puts it in group 3 of 6, group 1 being the genes least tolerant of losing a copy. Missense variants: 734 observed, 733.51 expected, observed/expected ratio (o/e) 1, 90% interval 0.94 to 1.06. Synonymous variants: 225 observed, 244.58 expected, observed/expected ratio (o/e) 0.92, 90% interval 0.82 to 1.03.
Homologues: Orthologues: chimpanzee ZNF681 (99% identical), macaque ZNF681 (85% identical), mouse Zfp738 (51% identical), mouse Zfp457 (48% identical), mouse Zfp595 (47% identical), rat AABR07009105.1 (36% identical), mouse Zfp953 (25% identical). Paralogues in human: ZNF724 (71% identical), ZNF85 (69% identical), ZNF429 (69% identical), ZNF43 (66% identical), ZNF254 (66% identical), ZNF726 (65% identical), ZNF728 (63% identical), ZNF93 (61% identical), ZNF708 (60% identical), ZNF493 (57% identical), ZNF676 (55% identical), ZNF492 (55% identical), and 164 more.